APP (amyloid beta precursor protein)
Diseases named in the same sentence as APP in open-access papers (continued):
Sharing a sentence is not in itself a finding about the gene and the disease.
cognitive decline (continued). "Interestingly, exosomes derived from hypoxia-preconditioned MSCs can rescue synaptic dysfunction and cognitive decline in an animal model of early-onset AD (APP/PS1 mice, which are double transgenic mice expressing a chimeric mouse/human APP, and a mutant human presenilin 1, PS1)." (PMID 31906013, 2019). "Since several mutations within the APP sequence have been shown to have an impact on BACE-1 cleavage affinity on APP, we analyzed a recently described APP mutation A673T that has been shown to protect against AD as well as against cognitive decline in the elderly independent of AD." (PMID 26895626, 2016). "The serotonergic system, classically involved in the depression/anxiety mechanisms, is now proposed to regulate Aβ precursor protein (APP) activity and metabolism, while Brain Derived Neurotrophic Factor (BDNF) has a relevance not only in MD, but also in depression-associated cognitive decline." (PMID 26869919, 2016). "We reported that amyloid precursor protein (APP), the Aβ source, possesses intracellular signaling that attenuates Aβ production and prevents cognitive decline in AD mice." (PMID 41630648, 2026). "APP/PS1 mice show early pathology by 4 months and measurable cognitive decline 6 months later in previous research." (PMID 40693114, 2025). "The oral administration of gallic acid disrupted the Aβ1–42 aggregation and decreased the neurotoxicity in a 4-month-old APP/PS1 transgenic mouse and reduced its cognitive decline." (PMID 41471791, 2025). "Reactive astrocytes are evident in the APP/PS1 mice when plaques start to form, coinciding with cognitive decline." (PMID 38675490, 2024). "In vivo: in APP/PS1 double-transgenic mice injected with pAAV-gfap:Hamp, induced a reduction of cognitive decline accompanied, Aβ plaques formation, iron levels, oxidative stress, neuroinflammation and neuronal death." (PMID 38913042, 2024). "Our data illustrate this link and are further strengthened by the fact that the male APP/PS1 mice at 7 months of age not only had lower SBP values, but also poor recognition of the novel object indicating that they were experiencing cognitive decline." (PMID 38862757, 2024). "Consistent with previous results of CC treated 7-month-old APP/PS1 mice, the MWM test indicated that early treatment of CC improved progressive cognitive decline of the AD mice." (PMID 39454957, 2024). "Our results showed that the deletion of SARM1 in APP/PS1 AD model mice led to a reduction in Aβ deposition, inflammatory infiltration, and neuronal death, thereby delaying cognitive decline." (PMID 37307837, 2024). "Compared with APP transgenic mice, APP/PRDX3 transgenic mice show less cognitive decline and reduced amyloid beta levels in the brain." (PMID 37762527, 2023). "APP/PS1 female mice were treated with CP2 or vehicle starting at 9 months of age, after the onset of cognitive decline and neurodegeneration, to test the efficacy of this novel therapeutic strategy under conditions most relevant to patients." (PMID 37190020, 2023). "Oxyphylla A reduced the expression levels of amyloid precursor protein (APP) and amyloid beta protein (Aβ) alleviated cognitive decline in SAMP8 mice." (PMID 36829795, 2023). "It is found that IL-17 is increased in APP/PS1 mice and Aβ-induced model mice and leads to neurotoxicity and cognitive decline through the IL-17/TRAF6/NF-κB pathway." (PMID 37441611, 2023). "On the other hand, the function of APP, which binds to BRI2, is presumed to play a significant role in the mechanism of cognitive decline." (PMID 36766796, 2023). "Nasal administration of IS@NP/KH to APP/PS1 mice, which express both mutant APP and presenilin, attenuates cognitive decline, improved motor function and decreased amyloid plaques in the brain." (PMID 34689261, 2022). "APP/PS1 and Tg6799 are both commonly used AD mouse models showing the age-related progression of Aβ plaque deposits in the brain and cognitive decline." (PMID 35326455, 2022).
cognitive decline (continued). "We also found that FSH exacerbated AD-like neuropathology and cognitive decline in 3xTg, APP/PS1, and APP-KI mice, while the inhibition of FSH action rescued this phenotype." (PMID 36052994, 2022). "Surprisingly, multifocal microinfarcts reduced Aβ deposition in the brain in male and female APP/PS1, which was more pronounced in females, while exacerbating cognitive decline more importantly in males." (PMID 35173711, 2021). "APP/PS1 mice were 12 months old, an age where cognitive decline and Aβ deposits are well-documented." (PMID 33978814, 2021). "Similar to APP/PS1 mice at the age of 2–3.5 month-old, hippocampus glucose metabolism in the SF brain was also increased, it matched with the cognitive decline in behavioral tests reported previously." (PMID 34992526, 2021). "Nonetheless, the reduced frequency of monocytes in response to microinfarcts seems to be less potent in female APP/PS1 mice, in which cognitive decline was moderate." (PMID 35173711, 2021). "The generation of Ly6Clow CX3CR1high and Ly6Chigh CX3CR1low monocytes have been reported to be progressively impaired in APP/PS1 mice, correlating with cognitive decline." (PMID 35173711, 2021). "For example, deletion of STAT3 in astrocytes in the APP/PS1 model of AD decreased beta amyloid plaque formation and ameliorated spatial learning and cognitive decline." (PMID 32192109, 2020). "The development of NLRP3 -/- x APP/PS1 transgenic rodent models demonstrates that by reducing inflammation in AD models, histopathology hallmarks and cognitive decline can be mitigated." (PMID 32033164, 2020). "The A673T (Icelandic or protective) mutation, which is COOH-terminal to the β-site of APP, decreases the affinity of APP for BACE1, and thereby reduces β-processing and protects against late-onset AD and normal cognitive decline." (PMID 32022689, 2020). "In APP/PS1 mice, FTS•B counteracted cognitive decline, ameliorated the deposition of Aβ and the phosphorylation of tau protein, and attenuated the activation of microglia and astrocytes in the cortex and hippocampus." (PMID 33059746, 2020). "Depletion of Tregs aggravates cognitive decline in APP/PS1/tau triple transgenic and APP/PS1 double transgenic mouse models of AD." (PMID 31736738, 2019). "We found that APP/PS1 mice spent more time locating the platform (escape latency) compared with wild-type (WT) mice, indicating a significant cognitive decline in terms of spatial learning." (PMID 30871577, 2019). "Aβ, the main component of plaques, is the result of the cleavage of amyloid precursor protein (APP) and accumulates both intra- and extracellularly leading to synaptic dysfunction, which is currently the best correlate of cognitive decline in patients." (PMID 30533998, 2018). "Intriguingly, with YXQN high-dose supplemented for 2 months, the spatial short- and long-term memory formation and retention of the APP/PS1 mice was similar to that of the littermates WT mice, suggesting that YXQN counteracts cognitive decline in APP/PS1 mice." (PMID 28603494, 2017). "Previous studies have found that wheel running exercise can prevent cognitive decline in transgenic AD mice, such as Tg2576 mice, APOE epsilon 4 mice and APP/PS1 double transgenic mice." (PMID 29029478, 2017). "We observed an overall cognitive decline in wild-type mice treated with STZ, with comparable performance to APP/PS1-Sham treated mice, and a worsening effect was observed in APP/PS1-STZ mice." (PMID 26156287, 2016). "g., cognitive decline, impairments in LTP and memory) are characteristic for all APP mutants and reveal a time depended development." (PMID 26834621, 2015). "Apparently, age-dependent hippocampal ECM accumulation is accelerated in APP/PS1 mice and contributes to early memory impairments, whereas later in the disease, other pathological mechanisms are responsible for further cognitive decline." (PMID 24974208, 2014).
cognitive decline (continued). "Transgenic mice overexpressing human FAD mutant APP (Tg2576 mice) display an Aβ-dependent enhanced caspase-3 activation, and Z-DEVD-fmk restores cognitive decline in Tg2576 mice." (PMID 23217200, 2012). "Moreover, we demonstrate that elevated REE, a suggested mechanism for cognitive decline in both humans with AD and in AD mouse models, is also normalized by VET in the APP/PS1Tg mice." (PMID 39898049, 2025). "While APP/PS1 and 5xFAD models exhibit temporal differences in amyloid pathology, both recapitulate gut-brain axis dysregulation characteristic of AD progression and share phenotypes of cognitive decline and neuroinflammation." (PMID 40822397, 2025). "Further investigation into the underlying mechanisms revealed that the signaling of tumor necrosis factor-α (TNF-α) was downregulated in the hippocampus tissues of APP/PS1;SARM1Nestin-CKO mice, thereby alleviating the cognitive decline, Aβ deposition and inflammatory infiltration." (PMID 37307837, 2024). "Unlike most other APP models, cognitive decline in Tg2576 mice manifested months prior to pathology whereas cognitive decline occurred in close proximity in other models." (PMID 38462606, 2024). "In contrast, Mohle and colleagues reported that DMF did not reduce cognitive decline and amyloid-β deposition in female APP/PS1 mice." (PMID 38383481, 2024). "On the other hand, although the 7 months old female APP/PS1 mice in our study did not exhibit significant cognitive decline, they had a significant increase in the hippocampus Aβ1-42 plaque burden." (PMID 38862757, 2024). "According to pedigrees, isolated cognitive decline occurred in 13/24 (54.2%) APP duplication families, with no reported ICH, whereas mixed presentation (cognitive decline in some affected relatives and ICH in others) occurred in 10 (41.6%) families." (PMID 37170141, 2023). "Expectedly, both A16 and Fab16 effectively rescued cognitive decline in APP/PS1 mice, as evaluated using Y-maze and NOR tests." (PMID 36693826, 2023). "In this case, we used the APP/PS1 mice that develop beta-amyloid deposits in the brain at 4 months of age, having a slower progression of the disease than the APPNL-G-F mice but having also a cognitive decline at this age." (PMID 37187754, 2023). "Here, we were able to demonstrate that BCAA-restricted diet for just two months substantially ameliorated AD-related brain pathology and cognitive decline in APP/PS1 mice that is independent of changes in body weight or food intake." (PMID 36359919, 2022). "NOR is the gold standard test for assessing cognitive decline and APP mice were able to differentiate between the novel object and the familiar object in response to MDP." (PMID 35883683, 2022). "Four of these studies show that caffeine alters APP processing to a non-amyloid pathway, reducing AD burden and cognitive decline." (PMID 35744865, 2022). "The escape latency on days 2–5 and the platform crossover number of the Ac group were drastically different from those of the Cc group, demonstrating that the cognitive ability of APP/PS1 mice was significantly reduced, which was in line with the pathological changes of the AD cognitive decline." (PMID 35992924, 2022). "While protective against Aβo-induced toxicity in cortical cultures, 14-3-3θ overexpression failed to rescue cognitive decline and pathologic changes in two APP mouse models." (PMID 35697511, 2022). "Consistent with this premise, human apoE4 expressed in mice seeded Aβ aggregation, and conversely, knockout of the mouse Apoe gene in transgenic mice expressing human amyloid precursor protein (APP) abolished amyloid fibril and plaque formation and cognitive decline." (PMID 35768831, 2022). "In APP mice, overexpression of CCL2 results in increased deposition of Aβ in the cerebral cortex and hippocampus, coinciding with enhanced accumulation of mononuclear phagocytes around senile plaques, and leading to cognitive decline." (PMID 35821178, 2022).
cognitive decline (continued). "In this study, we investigated the consequences of sporadic microinfarcts induced via the occlusion of the cerebral microvasculature on AD-like pathology in young male and female APP/PS1 mice, a widely used model characterized by progressive Aβ pathology and cognitive decline." (PMID 35173711, 2021). "Hence, CD33 knockout in the APP/PS1 mice attenuated Aβ plaque deposition and cognitive decline, respectively." (PMID 34211387, 2021). "Our findings suggest that DKK1 expression is potently induced in the brain of male APP/PS1 mice after microinfarcts, which may account for the exaggerated cognitive decline in males." (PMID 35173711, 2021). "As expected, the expression of SYN in the cortex in APP/PS1 TBI group mice was significantly decreased compared with that in the APP/PS1 group mice (APP/PS1 TBI: p < 0.05 vs. APP/PS1), which was indicative of further disruption of synapse formation and in parallel with cognitive decline." (PMID 34539542, 2021). "In the present study, we first reported that lentiviral vector-mediated miR-195 effectively rescued the cognitive decline of APP/PS1 mice by preventing the generation rather than eliminating the deposition of Aβ plaques." (PMID 33981225, 2021). "In recent years, a wealth of miRNA data has been accumulated, but there is no single microRNA that regulate APP processing and amyloid beta formation and cognitive decline." (PMID 31130840, 2019). "In addition, compared to wild-type (WT) mice, while brain perfusion was similar in APP/PS1 mice fed with a chow diet, NAFLD in APP/PS1 mice reveals cerebral hypoperfusion and furthered cognitive decline." (PMID 31130652, 2019). "However, APP/PS1 mice spent more time searching for the hidden platform than controls (p < 0.01 model group vs. control group), indicating a significant cognitive decline." (PMID 31607908, 2019). "In line with this, the whole‐brain levels of the pro‐inflammatory cytokines IL‐1β and TNF‐α, which have both been associated with the progression of Aβ deposition, neurodegeneration, and cognitive decline in AD, were reduced in APP/PS1‐Stat3KO compared to APP/PS1‐Stat3WT mice." (PMID 30617153, 2019). "Together, these results show that ES does not accelerate or aggravate the AD-related cognitive decline or the alterations in AHN in APP/PS1 mice." (PMID 29563870, 2018). "This hypothesis was later supported by the data indicating that the A673T substitution in APP, located adjacent to the BACE1 cleavage site and making the APP a less favorable substrate for BACE1, protects against cognitive decline and AD." (PMID 29636850, 2018). "In 5XFAD APP transgenic mice model of Familial AD, deletion of the EP3 receptor blocked induction of pro-inflammatory gene, protein expression, lipid peroxidation and cognitive decline." (PMID 28415673, 2017). "The strategy of targeting the APP 5′-UTR to reduce APP expression and Aβ amyloid formation has been validated by the usage of novel IRE chemical inhibitors to alleviate APP and amyloid levels as well as cognitive decline in the TgCRND8 AD mouse model." (PMID 29061112, 2017). "Additionally, intranasal administration BDNF in the APP/PS1 Tg mice decreased the Aβ deposition and reduced the cognitive decline of the mice." (PMID 28377712, 2017). "Moreover, the treatment with γ-secretase inhibitors was found to induce both long-term deficits and APP-CTF accumulation in mice and to accelerate cognitive decline in human." (PMID 27138984, 2016). "It should be noted that the contribution of abnormal APP metabolism to SI-induced cognitive declines of aged mice has not been addressed in the present study." (PMID 25568286, 2015). "The significance of APP processing and the importance of BACE results are evident from several studies focused on understanding the cognitive decline and the memory impairment observed in patients with chromosome 21 trisomy, where APP and BACE genes are encrypted." (PMID 25120477, 2014).
cognitive decline (continued). "In contrast, in the complete absence of apoE, the mutant APP gene and its product Aβ are harmless, generating neither amyloid deposits, synaptic disfunction, or cognitive decline, with one copy of apoE having an intermediate effect." (PMID 22844635, 2012). "The present results suggest that at least, on average, slow learning and inaccurate memory are common features of cognitive decline in adult APP/PS1 mice and old nonTg mice." (PMID 18716656, 2008). "The ablation of circulating CD8+ T cells in APP/PS1 mice does not reduce the Aβ load or cognitive decline but increases the expression of neuronal genes such as Arc and Npas4, suggesting that brain CD8+ T cells may modulate synaptic plasticity." (PMID 40993111, 2025). "A major factor contributing to cognitive decline in AD involves the processing of amyloid precursor protein (APP), where the balance between amyloidogenic and non-amyloidogenic pathways influences amyloid deposition, and affects synaptic function, contributing to neurodegeneration." (PMID 41302511, 2025). "In APP/PS1 mice, a well-known transgenic AD mice model, FNDC5 gene expression in the hippocampus showed a notable decrease compared to WT mice, and when they reached 6 months of age, APP/PS1 mice initiated the formation of amyloid plaques, experienced gliosis, and exhibited cognitive decline." (PMID 38985081, 2024). "Intraperitoneal administration of GM1 ganglioside to the APP/PS1 mouse model exhibited a reduction of the Aβ-40 and Aβ-42; however, a recent study showed that intraperitoneal GM1 administration caused pathological abnormalities in APP/PS1 mice and failed to rescue cognitive decline." (PMID 38623278, 2024). "Consistent with our observation, showed that using the 4–6-week-old AD mouse model (APP/PS1), the amplification of Tregs by peripheral chronic low-dose IL-2 administration restored cognitive functions, whereas the transient depletion of Tregs accelerated the onset of cognitive decline." (PMID 38352237, 2024). "Aβ peptides generated by the sequential proteolysis of amyloid precursor protein (APP) by β- and γ-secretases are particularly prone to aggregation, resulting in plaques that contribute to tau pathology, neuroinflammation, synaptic dysfunction, neurodegeneration, and cognitive decline." (PMID 39062541, 2024). "To evaluate the cognitive decline in APP/PS1 mice, we performed the NOR test." (PMID 38862757, 2024). "Insulin signaling affects amyloid precursor protein (APP) processing, favoring the non-amyloidogenic pathway in proper signaling, while disruptions shift it toward the amyloidogenic pathway, increasing Aβ production linked to cognitive decline." (PMID 38002034, 2023). "Focusing on the HIP, many researchers have shown that even in the absence of plaque during the earliest stages of AD, soluble forms of Aβ could drive neuronal hyperactivity in the HIP of APP/PS1 mice, which may confirm the increased GCD in the HIP along with cognitive decline." (PMID 37278043, 2023). "Moreover, the cognitive decline typical of the advanced phase of the disease, as observed by analyzing processes of hippocampus-dependent spatial learning is not prevented in APP/PS1tg x p75NTR KO mice." (PMID 37213691, 2023). "However, 14-3-3θ overexpression failed to reduce cognitive decline or Aβ pathology or affect synaptic density in either the J20 or APP KI models." (PMID 35697511, 2022). "Our findings that APP/PS1 mice are unable to utilize the spatial cues available to replace the use of random strategy as the training progresses indicate that although the animal can complete the task, a subtle but significant cognitive decline is already happening." (PMID 36135933, 2022). "While several APP-overexpressing mouse models have now been shown to harbor PAS granules in the molecular layer of the hippocampus, studies had not been conducted in tauopathy models, in which more severe cognitive decline and neurodegeneration is frequently observed." (PMID 35941704, 2022).